COA7 (cytochrome c oxidase assembly factor 7)
Description:
Required for assembly of mitochondrial respiratory chain complex I and complex IV.
Synonyms: C1orf163; RESA1; SELRC1; FLJ12439; SCAN3
Tractability: PROTAC: ubiquitination databases record sites on it; its protein half-life has been measured.
Gene: Protein-coding gene on chromosome 1 (52,684,449 to 52,698,355, reverse strand). Ensembl gene ENSG00000162377.
Subcellular location: Mitochondrion intermembrane space
Subcellular location (Human Protein Atlas): Mitochondria; Nucleoplasm
Gene Ontology:
Molecular function: protein binding; protein-disulfide reductase activity
Biological process: mitochondrial respiratory chain complex IV assembly; respiratory chain complex IV assembly
Cellular component: mitochondrial intermembrane space; mitochondrion
Genetic constraint (gnomAD): Loss-of-function variants: 10 observed, 19.57 expected, observed/expected ratio (o/e) 0.51, 90% interval 0.31 to 0.87. The upper end of that interval is the gene's LOEUF score, 0.87, which puts it in group 3 of 6, group 1 being the genes least tolerant of losing a copy. Missense variants: 235 observed, 292.42 expected, observed/expected ratio (o/e) 0.8, 90% interval 0.72 to 0.89. Synonymous variants: 93 observed, 110.76 expected, observed/expected ratio (o/e) 0.84, 90% interval 0.71 to 1.
Gene-disease validity (ClinGen):
ClinGen rates the evidence that COA7 causes each of these diseases.
mitochondrial disease (autosomal recessive): Definitive.
Homologues: Orthologues: chimpanzee COA7 (100% identical), dog COA7 (91% identical), guinea pig COA7 (91% identical), rabbit COA7 (91% identical), mouse Coa7 (90% identical), pig COA7 (90% identical), macaque COA7 (90% identical), rat Coa7 (90% identical), tropical clawed frog coa7 (65% identical), zebrafish coa7 (60% identical), Drosophila melanogaster Coa7 (36% identical), Caenorhabditis elegans coa-7 (31% identical).
Diseases named in the same sentence as COA7 in open-access papers:
COA7 is named in the same sentence as 17 diseases in open-access papers, as found by Europe PMC text mining. Sharing a sentence is not in itself a finding about the gene and the disease. The quoted sentences say what the papers report.
Leukoencephalopathy (3 papers, 2019 to 2024). This term describes abnormality of the white matter of the cerebrum resulting from damage to the myelin sheaths of nerve cells. "COA7 mutants result in COX deficiency causing leukoencephalopathies and peripheral neuropathies and this deficiency can be restored by inhibiting cytosolic degradation of COA7 indicating these mutations delay COA7 import into mitochondria which are still capable of contributing to COX assembly." (PMID 33008142, 2020). "Whole‐exon sequencing of a patient who was diagnosed with leukoencephalopathy recently revealed biallelic heterozygous mutations of COA7 that led to absence of the protein." (PMID 30885959, 2019).
neuropathy (2 papers, 2023 to 2024). A disorder affecting the nervous system that manifests with pain, tingling, numbness, and/or muscle weakness. "Another challenge that lays ahead is to integrate the pathways identified through human disease cohorts into known signaling pathways mediating axon degeneration (for example, are processes disrupted by new neuropathy genes like SORD or COA7 upstream or downstream of Sarm1)?" (PMID 37614471, 2023).
Parkinson disease (2 papers, 2023 to 2024). A progressive degenerative disorder of the central nervous system characterized by loss of dopamine producing neurons in the substantia nigra and the presence of Lewy bodies in the substantia nigra and locus coeruleus. "COA7 gene variants may have caused parkinsonism in this case because mitochondrial function-related genes, such as parkin and PINK1, are known causative genes in some familial Parkinson’s diseases." (PMID 37264311, 2023). "There have been reports suggesting that mutations in the SURF1, COX20, and SCO2 genes, which are involved in the assembly of COX along with COA7, can result in a decrease in the activity of MRC complex IV, leading to dystonia or parkinsonism." (PMID 37750949, 2024). "However, COA7 variants with parkinsonism or adult-onset type cases have not been described." (PMID 37264311, 2023).
spinocerebellar ataxia (2 papers, 2023 to 2024). "We have identified the cytochrome c oxidase assembly factor 7 (COA7) gene as a novel causative gene for spinocerebellar ataxia with axonal neuropathy type 3 (SCAN3)." (PMID 37750949, 2024). "Biallelic mutations in the COA7 gene have been associated with spinocerebellar ataxia with axonal neuropathy type 3 (SCAN3), and a notable clinical diversity has been observed." (PMID 37750949, 2024). "We conducted comprehensive genetic analyses on the COA7 gene within a large group of Japanese patients clinically diagnosed with inherited peripheral neuropathy or cerebellar ataxia." (PMID 37750949, 2024). "Individuals with variants of cytochrome c oxidase assembly factor 7 (COA7), a mitochondrial functional-related gene, exhibit symptoms of spinocerebellar ataxia with axonal neuropathy before the age of 20." (PMID 37264311, 2023).
generalized dystonia (1 paper, 2024). "We propose that COA7 should be considered as a new causative gene for infancy-onset generalized dystonia, and COA7 gene screening is recommended for patients with unexplained dysfunctions of the central and peripheral nervous systems." (PMID 37750949, 2024). "WES did not identify any known pathogenic mutations in genes associated with hereditary dystonia or familial Parkinson’s disease, suggesting that COA7 may be a new causative gene for infancy-onset generalized dystonia." (PMID 37750949, 2024).
Mitochondrial encephalopathy (1 paper, 2019). "Mutations in COA7 are associated with the defective assembly and function of respiratory chain complexes in patients diagnosed with mitochondrial encephalopathy." (PMID 30885959, 2019).
peripheral neuropathy (3 papers, 2020 to 2024). A disorder affecting the peripheral nervous system. "In another example, Cytochrome c oxidase assembly factor 7 (COA7) was identified from patient genomic analysis as a new causative gene for peripheral neuropathy." (PMID 37614471, 2023).
mitochondrial disease (1 paper, 2021). "Unexpectedly, the genetic investigation revealed a COA7-associated mitochondrial disease, which was confirmed functionally." (PMID 34322155, 2021). "Nevertheless, most published cases had a considerably later onset and milder phenotype, so that this case report expands the known genomic as well as the phenotypic spectrum of COA7 related mitochondrial disease." (PMID 34322155, 2021). "As such, this case report broadens the clinical and genetic spectrum of COA7-related mitochondrial disease." (PMID 34322155, 2021).
COA7 also shares sentences with these, for which no sentence is quoted: malaria (3 papers); Parkinsonism (2); axonal neuropathy (1); Brain atrophy (1); cardiomyopathy (1); cerebellar ataxia (1); dementia (1); Dystonia (1); hereditary spastic paraplegia (1).